EGFR (epidermal growth factor receptor)
Diseases named in the same sentence as EGFR in open-access papers (continued):
Sharing a sentence is not in itself a finding about the gene and the disease.
cancer (continued). "NSCLC CAFs co-cultured with EGFR mutant cancer cells activated the MET signaling pathway and/or FGF receptor, rescuing EGFR-positive cancers." (PMID 39834587, 2024). "The experiment showed promising antiproliferative effects against cancer cell lines, with low micromolar IC50 values against EGFR, compared to the reference doxorubicin." (PMID 39281035, 2024). "Studies have shown that co-inhibition of SHP2 and MAPK pathway signaling such as EGFR, KRAS, and MEK effectively inhibits cancer cell growth and counters adaptive cancer resistance." (PMID 39014007, 2024). "For example, the GM3 ganglioside can inhibit the autophosphorylation of the epidermal growth factor receptor (EGFR), thereby disrupting signaling pathways crucial for cancer progression." (PMID 39456198, 2024). "Hippo signaling components at the heart of oncogenic adaptations fuel the development of drug resistance in many cancers for targeted therapies including KRAS and EGFR mutants." (PMID 38607003, 2024). "Additionally, EGF secretion by cancer-associated fibroblasts could contribute to resistance in neighboring cancer cells, a challenge that erlotinib, unlike other EGFR inhibitors tested, could overcome." (PMID 38893104, 2024). "Patients with ALK-positive cancer (median [IQR] age, 55 years) were younger than patients with EGFR-positive (median [IQR] age, 62 years) and WT (median [IQR] age, 64 years) cancer." (PMID 38334998, 2024). "Burst keywords show that previous studies have concentrated on assessing the effectiveness of EGFR inhibitors and investigating combination therapies among patients with KRAS-mutant cancers." (PMID 38706597, 2024). "The resulting genetically engineered multifunctional immunomodulatory exosomes effectively inhibited EGFR-positive TNBC cells and elicited potent anti-cancer immune responses in vivo." (PMID 38835784, 2024). "These processes often converge on the epidermal growth factor receptor (EGFR), amplifying its activity in various cellular contexts, including cancer." (PMID 39768232, 2024). "EGFR and HER2-focused anti-NSCLC and antibreast cancer studies encouraged us to search for new potential agents." (PMID 39780846, 2024). "The epidermal growth factor receptor (EGFR) family ErbB1 and ErbB2, stem cell factor (SCF)-KIT, and vascular endothelial growth factor receptor 3 (VEGFR3) pathways, major pathways related to cancer aggressiveness, were downregulated." (PMID 38886756, 2024). "Our findings indicate that silibinin effectively suppresses the expression of EGFR mRNA, a crucial compound in the PAM signaling pathway, along with several downstream genes, including PI3K, AKT-1, PTEN, and mTOR mRNAs, in cancer cells." (PMID 38504785, 2024). "These lines of evidence suggest a link between EGFR expression and the progression of CD44+-mediated cancer stem cells." (PMID 38699644, 2024). "Nicotine enhances α7-nACh receptor expression and promotes the M2-type polarisation of microglia by disrupting EGFR signalling and STAT3 pathways, thus promoting cancer cell progression and metastasis." (PMID 39364322, 2024). "Peptides comprising PRM-containing C-terminal tail regions of EGFR, FGFR2 and HER2 were used as bait to affinity purify bound proteins from different cancer cell line lysates." (PMID 39165974, 2024). "Upon stimulation with EGF, EGFR activity is known to induce IRF1 gene cascades, largely through STAT1 phosphorylation/activation, in other cancer cell lines." (PMID 38339304, 2024). "Although EGFR favors the formation of homodimers, it is frequently observed in heterodimerization with HER2, which leads to drug resistance and cancer progression." (PMID 39742082, 2024). "M1231, a joint venture between Merck and Sutro Biopharma, is a bsADC targeting EGFR and mucin 1 (MUC1), which are highly co-expressed in cancers such as NSCLC, esophageal squamous cell carcinoma, HNSCC, TNBC, and ovarian cancer." (PMID 39065587, 2024).
cancer (continued). "Raf1, B-Raf, EGFR, SOS1, Bad, Myc, Jun, and Mcl1 were mapped to pathways related to apoptosis or cancers." (PMID 38643189, 2024). "Both EGFR and PDGFRA act as managing obvious prognostic factors in many cancers including glioblastoma." (PMID 39678505, 2024). "In the current study, we sought to investigate the efficacy of NIR‐PIT targeting EGFR and human epidermal growth factor receptor type‐2 (HER2) in senescent cancer and senescent stromal cells induced by γ‐irradiation in vitro." (PMID 38888415, 2024). "For example, in the case of insufficient effects of ERBB2 inhibition due to the compensatory overexpression of the EGF receptor (EGFR) in cancer cells, administration of the ERBB2 inhibitor, Herceptin, is often combined with suppressing EGFR activity." (PMID 39769257, 2024). "As a result, the cytotoxicity and effectiveness of MTX-211 in suppressing the activation of the EGFR and PI3K pathways were significantly attenuated in cancer cells overexpressing ABCG2." (PMID 38791198, 2024). "Among the top five EGFR inhibitors identified, afatinib, a second generation EGFR inhibitor approved by FDA for cancer treatment, was the top-ranking drug in the enrichment analyses that were included in multiple pathways involved in the pathogenesis of NIHL." (PMID 38896614, 2024). "Fourth, we investigated the binding affinities between the four crucial active ingredients and their potential targets such as EGFR and MET, both of which are well-known oncogenes in various cancers." (PMID 39628999, 2024). "At the molecular level, these alkaloids disrupt key signaling pathways in cancer cells, including mTOR, MAPK, EGFR, PI3K/AKT, and NF-κB." (PMID 39125943, 2024). "Epidermal growth factor receptor (EGFR) and aldehyde dehydrogenase 3 family member A1 (ALDH3A1) play important roles in cancer stem cell metabolism." (PMID 39513911, 2024). "ACSL4 was upregulated in EGFR-mutant lung ADC cell lines and the upregulation of ACSL4 led to a higher energy metabolism in EGFR-mutant cells, enabling cancer cells to enhance cell growth and acquire drug resistance." (PMID 38539505, 2024). "This study introduces a composite biomaterial, anti-epidermal growth factor receptor-conjugated manganese core phthalocyanine bismuth (anti-EGFR-MPB), synthesized for precise cancer imaging and treatment." (PMID 39525484, 2024). "For instance, PARP inhibitors combined with chemotherapy (TMZ, platinum salts, gemcitabine, etc.)or targeted drugs (EGFR inhibitors, HSP90 inhibitors, etc.)exert therapeutic effects on malignant tumors." (PMID 39552450, 2024). "Our data highlighted a significant enrichment of certain cellular adhesion molecules, including MCAM, EpCAM, ICAM-1, EGFR, and ALCAM, in cancer EVs relative to hTERT-immortalized MSC EVs." (PMID 38786083, 2024). "Despite the high initial effectiveness of first-line EGFR tyrosine kinase (TKI), the majority of individuals undergo cancer progression within a timeframe of 9 to 13 months after receiving therapy." (PMID 39324002, 2024). "The suppression of EGFR-regulated RAS-RAF-MAPK and PI3K-AKT-signaling pathways results in a reduction in cancer cell proliferation and increased cancer cell death." (PMID 38339275, 2024). "Curcumin and EGCG have emerged as promising candidates demonstrating efficacy as LDHA inhibitors and for overcoming EGFR-TKI resistance, particularly for cancer treatment." (PMID 38255882, 2024). "According to KEGG enrichment analysis, the primary signaling pathways involved include the cancer pathway, MAPK signaling pathway, AGE–RAGE signaling, EGFR, TNF, HIF-1, and the PD-L1/PD-1 checkpoint pathways." (PMID 39612458, 2024).
cancer (continued). "We have also determined antiproliferation effects in human cancer cell lines H1975 and HCC827 treated with 4, which show that this EGFR inhibitor is active at concentrations ~100–500 nM overall ~60-fold less potent than AZD9291 in both cell lines." (PMID 38378740, 2024). "Recently, antibody-conjugated nanoparticles, such as PD-L1, epidermal growth factor receptor (EGFR), and HER2, were developed for the cancer treatments." (PMID 39247806, 2024). "More importantly, EGFR, AKT1, and STAT3 are well-known biomarkers of cancer, but the effects of genistein on these targets remain elusive." (PMID 38731403, 2024). "Anti-EGFR mAbs have been found to be effective, especially in combination with other mAbs or TKIs, in TKI-resistant cancers and advanced NSCLC." (PMID 39336976, 2024). "Whereas EGFR overexpression is more frequently observed in LUSC than in LUAD, and aberrfant activation of EGFR plays a key role in cancer development." (PMID 39443476, 2024). "The key functional role as cytoplasmic chaperones is to regulate proteostasis by keeping substrate proteins (such as EGFR, MET, AKT, and many other kinases) in a folded and functional state, thus participating in human cancer development and progression." (PMID 39509399, 2024). "Both THBS1 and THBS2 share the TSR2 domain that interacts with the epidermal growth factor receptor (EGFR), which in turn is known to activate the PI3K/Akt/mTOR downstream signal pathway, known to be involved in cancer cell growth and survival." (PMID 38339060, 2024). "In various types of cancers, SEs control the expression of prominent tumor-promoting genes such as MYC, TAL1, STAT3 and EGFR, and mediate transcription dysregulation of cancer cells." (PMID 38254188, 2024). "Overall, the innovative integration of PDT with EGFR-TKI resistance overcoming, through an AND logic gate mechanism for drug release, makes it a promising system for cancer treatment." (PMID 39321294, 2024). "In summary, EGFR activation triggers a network of signaling pathways, including PI3K-AKT and MAPK, which drive cancer cell survival and proliferation when dysregulated." (PMID 39337496, 2024). "EGFR activation and subsequent intracellular signaling leads to cell proliferation and survival, benefitting the GBM cancer cells." (PMID 39329751, 2024). "This review explores EGFR and MPS1 as therapeutic targets in HNC, analyzing their molecular mechanisms and the effects of their inhibition on cancer cells." (PMID 39339232, 2024). "In bladder cancer, METTL1-m7G-mediated tRNA methylation promotes EGFR/EFEMP1 translation and thus promotes angiogenesis and cancer cell metastasis." (PMID 39019857, 2024). "The findings reveal a novel mechanism where H3K23ac/TRIM24 mediates EGFR-induced STAT3 activation, enhancing the oncogenic potential of the EGFR/STAT3 pathway in human cancer." (PMID 39160596, 2024). "These nuclides when attached to nanobodies are particularly useful for imaging cancer biomarkers like HER2,131 HER3,132 and EGFR,133 as well as immune checkpoints such as PD‐L1134 and CTLA‐4,135 and the tumor microenvironment." (PMID 39166870, 2024). "Cancer cells can release EGF-like peptides, acquiring the capacity of autocrine stimulation via EGFR-mediated signaling." (PMID 39329717, 2024). "Topological analysis of the PPI network, using the STRING database and Cytoscape 3.10.2, identified seven core targets crucial in cancer pathways: CYP3A4, PIK3R1, PIK3CD, ESR1, AKR1C3, EGFR, and CYP19A1." (PMID 39204124, 2024). "Compound 40 has been considered useful as a chemical probe to investigate human epidermal growth factor receptor (HER, ErbB) signaling in human breast and cancer malignancies that are resistant to treatment." (PMID 38535455, 2024).
cancer (continued). "In cancer, curcumin’s effectiveness is determined by examining its interaction with pivotal proteins like CDK2, CK2α, GSK3β, DYRK2, and EGFR, among others." (PMID 38474160, 2024). "We noticed that several cancer-related pathways were enriched, including JAK-STAT pathway, ERBB2 − EGFR and PI3K-AKT signaling." (PMID 39695095, 2024). "This approach is especially promising for cancers that overexpress specific receptors, such as HER2, EGFR, or EphA2, allowing immunotoxins to deliver highly potent agents selectively." (PMID 39685591, 2024). "EGFR-mediated HSP70 nuclear localization and HSP70-assisted assembly of the PCNA-centered replisome are important mechanisms for cancer-initiating cells to reduce replication stress for their proliferation." (PMID 39470734, 2024). "On the other hand, there are reports that EGFR, PI3K/AKT, and RAS/MAPK signaling pathways are key regulators of metabolism, including lipid metabolism, in cancer." (PMID 38874588, 2024). "Overexpression of ZNRF3 reduces EGFR levels and suppresses cancer cell growth in vitro and in vivo, whereas knockout of ZNRF3/RNF43 stimulates cell growth and tumorigenesis through upregulated EGFR signaling." (PMID 38260423, 2024). "By conjugating with panitumumab, a human Epidermal Growth Factor Receptor (EGFR)-targeted monoclonal antibody, NIR duocarmycin photorelease (NIR-DPR) showed significant anti-cancer efficacy in vivo." (PMID 38915782, 2024). "As a robust irreversible EGFR/HER2 dual TKI, PYR has shown remarkable responses in many advanced cancers even with previously failed EGFR/HER2 targeted treatments." (PMID 39107736, 2024). "There are at least 11 bsAbs targeting CD19 × CD3, EGFR × MET, gp100 × CD3, CD20 × CD3, BCMA × CD3, CTLA-4 × PD-1, CD20 × CD3, and GPRC5D × CD3, which have been approved for treatment of various cancers." (PMID 38257366, 2024). "For instance, proteins like HSP70 and EGFR are highly expressed in HCC-derived exosomes, promoting cancer cell migration and invasion." (PMID 39497820, 2024). "In another cell cluster, we also discovered the high expression of well-known cancer stem cell markers SOX2 and EGFR (Epidermal Growth Factor Receptor), indicating abnormal proliferation and malignancy in these cell clusters." (PMID 39257581, 2024). "Among patients with NSQ cancer and known EGFR and ALK status, 5304 individuals (40.5%) were WT, 6866 individuals (52.5%) were EGFR-positive, and 914 individuals (7.0%) were ALK-positive." (PMID 38334998, 2024). "Poziotinib, a dual inhibitor of EGFR and HER2, has shown efficacy against various types of cancers in phase 1 studies." (PMID 39239273, 2024). "Together, these data highlight ZNRF3 and RNF43 as novel E3 ubiquitin ligases of EGFR and establish the inactivation of ZNRF3/RNF43 as a driver of increased EGFR signaling, ultimately promoting cancer progression." (PMID 38260423, 2024). "EGFR induces PD-L1 via the IL-6/JAK1/STAT3 pathway 63, which reciprocally drives PD-L1 phosphorylation (Tyr112) to evade cancer immunosurveillance." (PMID 38505617, 2024). "We also identified that compound IV inhibited EGFR (IC50 = 4.34 μM) and HER2 (IC50 = 2.28 μM) and showed significant anti-NSCLC and antibreast cancer effects." (PMID 39780846, 2024). "Acting downstream of multiple kinases and growth factor receptors, including but not limited to PDGFR, EGFR and IL-6, STAT3 is an important mediator of gliomagenesis through its role in modulating cancer cell survival, invasiveness, and immune evasion." (PMID 38615034, 2024). "EGFR is a tyrosine kinase-type receptor that is commonly activated or overexpressed in a variety of cancers, and the MAPK/ERK signaling pathway mediates the biological effects of EGFR activation." (PMID 38762741, 2024).
cancer (continued). "Consequently, ALK fusion proteins may circumvent anti-EGFR inhibition to activate downstream components of EGFR, thereby promoting cancer cell proliferation and survival, which could explain the possible mechanism of inner resistance to Cetuximab observed in our patients." (PMID 38740834, 2024). "One of its upstream signals is EGFR, and inhibition of EGFR inhibits morphine-induced activation of ERK1/2 signalling in a mouse model of cancer pain." (PMID 39669194, 2024). "Frequent dysregulation and genomic alterations of RTKs, particularly HER2, EGFR, and MET, are involved in the development of various benign conditions and several forms of malignant tumors." (PMID 39551787, 2024). "Specifically, ALYREF binds to the m5C-modified EGFR mRNA, enhancing its stability and therefore contributing to the tumorigenesis of LIHC cancer cells." (PMID 38164181, 2024). "The GAs interact with receptor tyrosine kinase (RTK) and modulate cancer pathways through the IR, IGFR-1, IGFR-2, VEGFR-1, VEFGR-2, and EGFR signaling networks." (PMID 39484305, 2024). "Branched and linear conjugates of the EGFR-targeting aptamer GR20 and a model unstructured oligonucleotide were synthesized and tested on various cancer cell lines." (PMID 39598559, 2024). "With minimal overlap in EGFR and HER2 antibody-mediated toxicities, and high frequencies of EGFR and HER co-expression in PDAC and other cancers, the development of therapies that target both proteins is appealing." (PMID 38650005, 2024). "As anticipated, MTX-211 effectively suppressed the phosphorylation levels of EGFR and AKT in both S1 and S1-MI-80 cancer cells in a dose-dependent fashion." (PMID 38791198, 2024). "TAM-derived EGF activated EGFR on cancer cells, then increases expression of VEGF-C and VEGFR3 in cancer cells." (PMID 39513610, 2024). "There are four anti-EGFR medications approved by the FDA, which are cetuximab, panitumumab, gefitinib, and erlotinib, for treating certain cancers." (PMID 39335615, 2024). "Conversely, in tumors with downregulated USP21, EGFR undergoes ubiquitination and subsequent degradation within MVB-lysosome vesicles, leading to reduced cancer progression due to diminished EGF engagement." (PMID 39695128, 2024). "EGFR signaling promotes survival and resistance to ALK inhibitors in EML4-ALK+ cancer cells in vitro, in animal studies, and in patients." (PMID 39488530, 2024). "A variety of effective and well-tolerated TKIs targets, including EGFR, ALK, ROSI, HER2, etc., have emerged continuously, and promoted significant progress in cancer treatment." (PMID 36798829, 2023). "Driven by the goal of targeting key cancer drivers, we identified 16 and 28 E3 ligases targeting KRAS and EGFR, respectively." (PMID 37845222, 2023). "Gene expression analysis identified a large number of differentially expressed genes after AV25R exposure and significant differentially regulated cancer-related signaling pathways, such as VEGFA-VEGFR2 signaling and the EGF/EGFR pathway." (PMID 38138609, 2023). "A series of 1,5-diarylpyrzole derivatives targeting EGFR and JNK-2 were developed and synthesized and biologically evaluated for their anticancer activity against a panel of five cancer cell lines, namely DLD-1, Hela, K562, SUIT-2, and HepG2." (PMID 37764297, 2023). "To confirm the increase in PAI-1 expression in cancer cells with tolerance to EGFR-TKIs, we compared the PAI-1 expression in EGFR-TKI-tolerant cells to that in control cells in vitro." (PMID 36831438, 2023).